VEGFA (vascular endothelial growth factor A)
Diseases named in the same sentence as VEGFA in open-access papers (continued):
Sharing a sentence is not in itself a finding about the gene and the disease.
tumor (continued). "The pH-sensitive and tumor-targeted nanoparticle BAF312@cRGD-CaP-NP shows greatly improved antitumor efficacy and suppression of angiogenesis via the S1PR1/P-STAT3/VEGFA axis in BRCA, especially in TNBC." (PMID 34059068, 2021). "Compared with TIE2− TAMs, TIE2+ TAMs within the same tumor express higher levels of pro-angiogenic genes, including MMP9, VEGFA, COX2, WNT5A, and PDGFB." (PMID 34603327, 2021). "HIPK2 can inhibit several angiogenic genes, including MMP10 and VEGF, to inhibit angiogenesis, while exomi-1229 promotes CRC tumour angiogenesis by inhibiting HIPK2 and inhibiting P-AKT and VEGFA in CRC." (PMID 33865381, 2021). "VEGFA, a member of the VEGF family, is one of the key regulators of tumor angiogenesis and plays a role in cancer by stimulating VEGF receptor (VEGFR) on tumor cells." (PMID 33435917, 2021). "The expression of VEGFA and VEGFR2 mRNA is upregulated in most human tumours, correlating with tumour recurrence, metastasis and poor prognosis." (PMID 33655556, 2021). "Neutrophils also promote tumor invasion and angiogenesis through production of MMP9, elastase, VEGFA and oncostatin M." (PMID 34322780, 2021). "Cisplatin further enhanced the positive correlation between the area of tumor colonies and gene expression of PGE2S, EGFR, FOLR1, EP3, COX2, and VEGFA in cancer cells, highlighting the importance of these genes in treatment resistance." (PMID 33671869, 2021). "Again, this primarily occurs through IFN-mediated reduction in VEGFA and HIF1α transcription, with lower levels of VEGF mRNA detected in tumour samples following Type I IFN therapy, as compared to diagnostic samples." (PMID 34778087, 2021). "As previously reported, VEGFA is one identity signature in RCC angiogenesis, participating in tumor proliferation and distal metastasis." (PMID 33634984, 2021). "Most DEGs in the brown module were involved in tumor progression or metastasis (module membership >0, cor = 0.83, p < 2.2e-16), including NOTCH3, VEGFA, SNAL1, TGFBR1, and MMP14, thereby confirming the correlation of some DEGs with phenotypes." (PMID 34458146, 2021). "All these results suggest that S1PR1 affects tumor growth and vascular formation through the S1PR1/P-STAT3/VEGFA pathway." (PMID 34059068, 2021). "Given that SIRT2 is thought to promote vascular endothelial growth factor A (VEGF-A) signalling and endothelial-like tube formation in tumour angiogenesis, specific inhibitors have also been developed." (PMID 34880756, 2021). "gaMSCs secrete several cytokines and exosomes into the tumour microenvironment, such as IL-6, CCL-5 and VEGFA." (PMID 34256854, 2021). "Tumor-derived lactate, a byproduct of tumor glycolysis, leads to M2-like TAM polarization by activating HIF-1α and subsequent inducing ARG1 and VEGFA." (PMID 34389031, 2021). "Overexpressed vascular endothelial growth factor A (VEGFA) and highly activated signal transducer and activator of transcription 3 (STAT3) contribute to the unrestricted tumor growth and vascularization of BRCA, especially TNBC." (PMID 34059068, 2021). "In order to assess the possible role of each drug on brain metastasis, eight protein/gene effectors known to have a more important role in brain metastasis than in primary tumours were considered: FGFR1; Ki-67, ROBO1; S100A7; S100B; SIRT1; SLIT2; and VEGFA." (PMID 33659043, 2021). "The increased VEGFA is secreted extracellularly via exosomes, an event potentiated by the interaction of FOXM1 with VPS11, eventually promoting tumor angiogenesis." (PMID 33314660, 2021). "Through the effects of soluble factors and matrix altering enzymes such as vascular endothelial growth factor A and TGF-β, and matrix metalloproteinases (MMP), CAF induce tumor progression by promoting angiogenesis, tumor growth and invasion." (PMID 34439387, 2021).
tumor (continued). "Triptolide also reduced tube formation of human umbilical vein endothelial cells and angiogenesis through inhibiting the ERK1/2-HIF1-α-VEGFA axis; triptolide decreased VEGFA, cluster of differentiation (CD) 31 in MDA-MB-231 tumor." (PMID 34948368, 2021). "Inhibition of XBP1 in TAMs downregulated the expression of pro-tumor cytokines, such as IL-4, IL-6, MMP2 and VEGFA." (PMID 34667145, 2021). "It has been demonstrated that an upregulated expression of VEGFA in TIE2(hi)-derived macrophages induced the proliferation of endothelial cells and by this, led to tumor neovascularization." (PMID 34965886, 2021). "In the current study, we investigated the clinical significance of tumor expressions of HIF1A, VEGFA, CA9, and SLC2A1 assessed by IHC and markers of systemic inflammation (NLR and CRP) in pediatric patients with MPNST." (PMID 33810575, 2021). "Vascular endothelial growth factor A (VEGFA) and its receptor VEGFR2 are the main drivers of tumor angiogenesis and the main targets of antiangiogenic therapies." (PMID 33921219, 2021). "AML cells secrete vascular endothelial growth factor A (VEGF-A), which promotes both leukaemic cell proliferation and tumour-supportive angiogenesis." (PMID 34206957, 2021). "Some studies on biochemical changes in tumor cells have shown that high hypoxia-inducible factor 1α (HIF-1α) and vascular endothelial growth factor A (VEGF-A) expression in viable tumors is conducive to tumor angiogenesis." (PMID 34900679, 2021). "This circRNA also correlated with advanced tumor, node, metastasis (TNM) stage, further establishing VEGFA as a crucial proangiogenic factor." (PMID 34205978, 2021). "Another study investigated the tumor-suppressive mechanisms of ACE2 via angiogenesis and tumor invasion, and found these to be mediated by regulation of MMP-2, MMP-9, and VEGFa." (PMID 33513805, 2021). "Each CD44+ cell-type functions immunosuppression through different ways: CD44+ tumor cells express CD276, IL13, VEGFA, and IDO1; CD44+ TAMs express IL10, TGFB1, VEGFA, and HAVCR2; CD44+ T cells express CD274, TGFB1, CTLA4, LAG3, and PDCD1." (PMID 35187044, 2021). "Its induction in endothelial cells has been shown to suppress tumor angiogenesis via reduction of mTOR-mediated phosphorylation and activation of STAT3 and resulting VEGFa expression." (PMID 34128833, 2021). "The increased expression of VEGFA in the tubular glands and VEGFR2 in the endothelium of GC samples mainly in the T2, T3 and T4 stages of tumor progression has been reported previously." (PMID 35082831, 2021). "Accordingly, dual blockade of VEGFA and ANG2 has demonstrated superior preclinical results through increased T cell tumor infiltration and myeloid repolarization." (PMID 34868044, 2021). "Genes in cluster 4 associated with cancer tissue (0.83) included many oncogenes: NOTCH3 signaling promotes tumor growth in CRC, whereas MMP14 and VEGFA are correlated with poor prognosis." (PMID 34458146, 2021). "Siponimod (BAF312) is a selective antagonist of S1PR1, which inhibits tumor growth and angiogenesis in vitro by downregulating the S1PR1/P-STAT3/VEGFA axis." (PMID 34059068, 2021). "Although NRPa-308 represents an interesting hit if tumor cells express both NRPs and their ligands VEGFA/VEGFC, specific drugs targeting NRP1 should be more appropriate if only NRP1/VEGFA is present." (PMID 33461580, 2021). "MiR-205 is another tumor suppressive molecule that targeted the action of both YAP1 and VEGFA and inhibited cell proliferation, cell cycle progression, and angiogenesis." (PMID 35186709, 2021). "A previous study applied chromatin immunoprecipitation assays to reveal that the STAT3 protein binds to the VEGFA promoter in vivo and found that constitutive STAT3 activity upregulates VEGFA expression and increases tumor angiogenesis." (PMID 34059068, 2021). "On the other hand, VEGFA and FABP6 genes are overexpressed in tumour tissue, which makes them possible candidates for inhibitory therapy." (PMID 32640984, 2020).
tumor (continued). "Metformin's decrease in hypoxia has been shown to inhibit hypoxia-inducible factor 1 (HIF1) and vascular endothelial growth factor A (VEGFA) driven angiogenesis; there is also evidence for a direct anti-tumor effect on endothelial cells." (PMID 33194937, 2020). "Consistent with the in vitro gene expression data for VEGFA and VEGFB showing induction after IL-21 treatment of Farage cells, in vivo we observed promotion of tumour angiogenesis." (PMID 32704112, 2020). "Tumor-associated macrophages secrete multiple angiogenic factors, e.g., vascular endothelial growth factor-A (VEGF-A) and matrix metalloproteinase 9 (MMP9), which induce blood vessel initiation and extension, as well as tumor cell metastasis to new sites." (PMID 33086476, 2020). "Within the tumor tissues, the RKO/ETV5+Bev group exhibited higher expression of VEGFA and CD31 than that exhibited by RKO/Vector+Bev group." (PMID 33099574, 2020). "Phenomenon was shown in melanoma where highly expressed exosomal miR-155 inhibits the expression of SOCS1, activates the JAK2/STAT3 pathway, up-regulates the expression of FGF2, VEGFA and MMP9 in CAFs, and promotes the formation of blood vessels in the tumor." (PMID 32299469, 2020). "Therefore, the Peptibody with bFGF/VEGFA might be used as a therapeutic tumor vaccine." (PMID 32944017, 2020). "After ZLM-7 treatment, protein expression of Sp1, VEGFA and MMP-2 in tumor tissues decreased when compared to control group." (PMID 33187481, 2020). "Hypoxia recruits TAM precursors from bone marrow to tumor lesion, through multiple mechanisms such as releasing chemoattractants like CCL2, CCL5, CXCL12, VEGFA, and endothelin and liberating some cellular contents like DAMPs from the hypoxic dying cell." (PMID 33505964, 2020). "Overexpression of VEGFA promotes angiogenesis, EMT and activates Ras/ERK signaling cascade, hence inducing tumor development." (PMID 32518520, 2020). "Vascular endothelial growth factor A (VEGFA), a major stimulator of tumor angiogenesis, as well as vascular endothelial growth factor receptor (VEGFR), are found to be overexpressed in most solid tumors 2,3." (PMID 32550907, 2020). "Tumor-derived TGF-β, together with other factors, such as VEGFA and TNFα, stimulates the release of chemoattractants, such as S100A8 and S100A9, that mediate the recruitment of immune cells in the pre-metastatic niche." (PMID 32397392, 2020). "ICAM‐1 expressed on LSECs promoted secretion of IL‐6, prostaglandin E2, VEGF, and MMP2 by tumor cells, which in turn induced VEGFA and MMP2 secretion by HSCs." (PMID 33252863, 2020). "miR-497 targets multiple genes, including VEGFR2, VEGFA, AEG-1, and HIF-1α to inhibit tumor angiogenesis." (PMID 32993787, 2020). "VEGFA expression can increase as a result of the long non-coding RNA (lncRNA) 00511 in PDAC, which finally promotes tumor progression." (PMID 33302876, 2020). "Further analyses revealed a stalled tumor angiogenesis, marked by decreased tumor oxygenation, CD31 immunostaining and VEGFA mRNA expression." (PMID 32545251, 2020). "CAFs isolated from anti-VEGFA resistant tumors, exhibit high levels of ANG2, and PDGF promoting tumor growth." (PMID 32775327, 2020). "TCGA dataset mining was performed using UALCAN to shown that abnormal expression of the hub genes, including CDK1, VEGFA, PRDM10, RUNX1, CDK6, HSP90AA1, and MYC, were significantly up-regulated between ESCA primary tumor and normal tissues." (PMID 32662828, 2020). "VEGFA/VEGFR2 signaling is a crucial downstream pathway of HGF/c-Met axis and plays a vital role in tumor angiogenesis." (PMID 32083078, 2020). "Bevacizumab by specifically inhibiting the binding of VEGFA to its receptor VEGFR2 present on ECs, blocks signaling pathways involved in ECs proliferation and subsequently tumor angiogenesis." (PMID 32775327, 2020). "The signalling pathway involving VEGF/VEGFA and VEGFR is a promising target for cancer treatment, as it has been identified as the main regulator of tumour angiogenesis." (PMID 33067558, 2020).
tumor (continued). "Using the Clinical Proteomic Tumor Analysis Consortium (CPTAC) Confirmatory/Discovery dataset, we found that VEGFA protein in ccRCC patients' tumor tissues was substantially increased compared to that in normal tissues." (PMID 33224312, 2020). "Among these proteins related with vessel growth, vascular endothelial growth factor A (VEGF) has been shown to be the most significant angiogenic factor, secreted by tumor." (PMID 32824997, 2020). "As NF-kB signaling is a well-known pathway for promoting tumor angiogenesis and results showed increased total VEGF and VEGFA expression after CYLD knockout, tumor microvessel formation was investigated by IHC staining of Cd34 in xenografts." (PMID 32708712, 2020). "VEGFA and VEGFC, two members of the VEGF family, have been reported to act as factors that contribute to tumor angiogenesis." (PMID 33046994, 2020). "Using total protein from HCC827 xenograft tumour tissues, we found that Afatinib inhibited the phosphorylation of JAK1,2, STAT3, and FAK, the protein expression of LYVE-1, VEGFR2, VEGFR3, VEGFC, VEGFA, and CCR7." (PMID 31892990, 2020). "Western blot analysis further indicated that inhibition of miR-183-5p led to a down-regulation in the expression of VEGFA, VEGFAR2, ANG2, PIGF, MMP-2 and MMP-9 along with up-regulated FOXO1 expression in tumor tissues (p < 0.05)." (PMID 32364530, 2020). "Preclinical studies recently showed that simultaneous blockade of VEGFA and ANG2 inhibits angiogenesis and tumor growth." (PMID 32775327, 2020). "Accumulated evidence has demonstrated that HIF-1α has a dominant role in tumor progression, and HIF-1α-regulation of expression of VEGFA is regarded as the main inducer of angiogenesis." (PMID 32273947, 2020). "These bevacizumab-adapted cells secrete more VEGFA, VEGFB, VEGFC, and PlGF, which induce migration of tumor cells and angiogenesis of endothelial cells in this medium in comparison with the parental cells." (PMID 32560565, 2020). "In relation to the malignancy grade of the tumor, mRNA levels of SEMA3B, SEMA3C, SEMA3D, SEMA3G, PLXNA2, and CDH1 decreased while mRNA levels of SEMA3F, NRP1, ITGB3, ITGA5, and VEGFA increased with the increase of the tumor malignancy (p < 0.05)." (PMID 33036421, 2020). "Along the transition from M1 to M2 state, macrophages acquired features that promote tumor invasion, metastasis, and immunosuppression with upregulated genes like MMP14, VEGFA, and MRC1." (PMID 33298893, 2020). "Anti-angiogenics, through hypoxia and HIF1α activation lead to the production of VEGFA and SDF1 by tumor cells triggering mobilization and recruitment of EPCs." (PMID 32775327, 2020). "Therefore, based on results of previous studies and our preliminary experiment, we hypothesized that in NF-PitNET, SDF-1α may regulate the production of its target protein VEGFA by regulating the level of miR-134, and subsequently mediate tumor cell proliferation, migration, and invasion." (PMID 33362712, 2020). "It became apparent that tumor size and weight were markedly reduced in mice injected with oe-IRAIN-transfected cells, which was rescued by treatment with oe-VEGFA." (PMID 32983957, 2020). "The expression of VEGFA, as well as FGF-2, is also triggered by the fibronectin extra-domain B, the tumor-specific isoform of fibronectin, and was shown to increase esophageal cancer vascularization." (PMID 32456248, 2020). "Glioma cancers have also reported the overexpression of VEGFA protein which is tumor grade based and miR-205 directly binds to the 3′ UTR site of VEGFA gene, and further, downregulates the expression of VEGFA at both gene and protein levels." (PMID 32854238, 2020). "Expression levels of VEGFA, NFE2L2, miR-17-5p, and miR-612 in the tumor tissues, colloid goiter, and their respective adjacent tissues were compared to those observed in the normal tissues." (PMID 32824922, 2020). "Simultaneous blockade of VEGFA and ARP2/3, VEGFA and c-MET or VEGFA and ZEB2 suppresses tumor invasion." (PMID 32775327, 2020).
tumor (continued). "VEGFA and ANG2 promote neovascularization and ANG2 plays a key role in tumor relapse following anti-VEGFA treatment." (PMID 32775327, 2020). "Overexpressed VEGF (Vascular Endothelial Growth Factor) proteins, including VEGFA, VEGFB, VEGFC, VEGFD, VEGFE, and PIGF in tumor cells, are responsible for induced neovascularization." (PMID 30682877, 2019). "An IHC analysis of markers revealed that Ki-67, VEGFA and HIF1A expression were decreased in the corresponding tumors in tumor-bearing mice treated with bevacizumab, docetaxel, or their combination." (PMID 31018595, 2019). "The genes most frequently showing CNGs in HAS tumour tissues were TOP1 (50.0%), STK4 (45.5%), CDKN1B (40.9%), H3F3A (36.4%), MYC (22.7%), CCNE1 (22.7%), NFKBIA (22.7%), VEGFA (18.2%), CCND3 (13.6%), and E2F1 (13.6%)." (PMID 30989433, 2019). "In conclusion, our study demonstrates that low expression of CDK5RAP3 in GNEC activates the AKT/HIF-1α/VEGFA signaling pathway, increasing secretion of VEGFA from GNEC cells into the tumor microenvironment and promoting tumor angiogenesis." (PMID 31728130, 2019). "An array of tumor-derived chemoattractants such as CSF1, CSF2, CCL2, VEGFA, and SEMA3A contribute to the recruitment of monocytic precursors, resulting in TAMs accumulation." (PMID 31406165, 2019). "In this study, we examined the effect of EHD1 on tumor angiogenesis in NSCLC and found that EHD1 induces NSCLC angiogenesis by upregulating VEGFA expression." (PMID 31023336, 2019). "Overexpression of MT1-MMP increased the transcription of vascular endothelial growth factor A (VEGF-A) in MCF-7 and U251 cells and, concurrently, tumor growth, angiogenesis, and metastasis." (PMID 31137480, 2019). "Bevacizumab is an antibody binding specifically to the circulating vascular endothelial growth factor A (VEGF-A) and inhibiting tumor angiogenesis." (PMID 31366114, 2019). "In these cases, bevacizumab, a monoclonal antibody targeting vascular endothelial growth factor A (VEGF-A), is an off-label treatment option that can slow tumor growth." (PMID 31291992, 2019). "In response, vascular endothelial growth factor A (VEGF-A) expression, the main angiogenic factor, that is a Hif-1α-regulated protein, is reduced with positive effects on tumor vascular maturation and patency." (PMID 32118030, 2019). "Consistently, we found that Akirin2 overexpression upregulated, whereas endogenous Akirin2 knockdown eliminated VEGFA expression and angiogenesis through the IL-6/STAT3 signaling pathway, and thus facilitated tumor growth, invasion, and metastasis." (PMID 30886152, 2019). "The CA9 mRNA level was also correlated with the mRNA expression of other HIF1 target genes in the investigated tumor samples such as glucose transporter 1 (Glut1≙ SLC2A1), glyceraldehyde-3-phosphate dehydrogenase (GAPDH), VEGFa and with miRNA-210 expression." (PMID 30654595, 2019). "The proangiogenic role of EHD1 was confirmed in xenograft tumor models, and immunohistochemistry (IHC) analysis confirmed that EHD1 expression was positively correlated with VEGFA expression, microvessel density (MVD) and β2AR expression in patient specimens." (PMID 31023336, 2019). "On the other hand, a hypoxia gene expression signature that included VEGFA and CA9 was significantly higher in low resource tumours." (PMID 31648981, 2019). "Conversely, overexpression of FOXM1 (SCC-25 FOXM1 #2) in SCC-25 cells increased target gene transcripts involved in tumorigenesis (VEGFA and AURKB) and decreased those related to tumor suppression (TRAIL Receptor 1 and 2)." (PMID 30978209, 2019). "In contrast, NCOA2, VEGFA, ACPP, KLF4, and TMPRSS2 had significantly higher tumor vs. normal ratio in BCR cases." (PMID 31741711, 2019). "Consistent with our observations in tumor cell lines and xenograft models, the distribution and intensity of EHD1 were positively correlated with β2AR, VEGFA and CD31 in NSCLC tissue specimens." (PMID 31023336, 2019).